PIK3CA (phosphatidylinositol-4,5-bisphosphate 3-kinase catalytic subunit alpha)
Diseases named in the same sentence as PIK3CA in open-access papers (continued):
Sharing a sentence is not in itself a finding about the gene and the disease.
tumor (continued). "Isogenic conversion of a PIK3CA-wild-type tumor into a PIK3CA H1047R-mutated tumor promotes sensitization to the anti-cancer effects of metformin." (PMID 23986086, 2013). "Overall, given the association between ERα positive tumours and increased PIK3CA mutation frequency in FBC, one would assume an increased rate of PIK3CA mutation in MBCs." (PMID 23971979, 2013). "There was significant absence of p4EBP1 nuclear (P = 0.009) or cytoplasmic (P = 0.006) staining and up-regulation of pS6 (P = 0.024) in tumours with PI3KCA somatic mutations when compared with PIK3CA wild type." (PMID 23971979, 2013). "Of all 105 tumors with PIK3CA mutations, 78 (74%) had a mutation within the helical domain of exon 9, with 1 tumor possessing 2 mutations, and 24 (23%) had a mutation in exon 20 catalytic domain." (PMID 23785428, 2013). "Genotyping performed on tumor from the autopsy revealed a PIK3CA exon 20 H1047R (catalytic domain) mutation in the primary tumor, lung metastasis, and liver metastasis." (PMID 23766666, 2013). "While there is some suggestion of a more aggressive phenotype or of tumour heterogeneity in cases with dual PIK3CA mutations, the clinical significance of this is also unclear due to the infrequency of this observation." (PMID 23971979, 2013). "A recent meta-analysis has supported these results, showing an objective response rate of 0% in patients whose tumours harboured a PIK3CA exon 20 mutation." (PMID 23356214, 2013). "After restricting the analysis to patients with a BRAF wild-type tumor, PIK3CA mutation was significantly associated with poorer overall survival (HR 1.51, 95% CI 1.04–2.19, P = 0.03) compared with wild-type PIK3CA." (PMID 23785428, 2013). "No improvement in precision of class partition was achieved on inclusion of either PIK3CA or ERBB2 aberrations as additional layers of information to the group of tumor samples with gene mutations." (PMID 23226389, 2012). "Although no statistical significance was noted, there was a positive association of PIK3CA mutations and amplification with tumor differentiation." (PMID 22292935, 2012). "Targeted sequencing of the helical and kinase domains of PI3K revealed that PIK3CA gene mutations were present in 44 of the 190 analysed tumours (23.2%)." (PMID 22949056, 2012). "The PIK3CA H1047R mutation was detected in 4 of 19 (21.5%) tumor specimens and 3 of 19 (15.8%) cpDNA samples, with concordance between 3 of 4 (75%) matched FFPE and cpDNA specimens." (PMID 23144797, 2012). "Dual PI3K/mTOR inhibitors have demonstrated significant, concentration-dependent cell proliferation inhibition and induction of apoptosis in a broad panel of tumor cell lines, including those harboring PIK3CA activating mutations." (PMID 23085539, 2012). "In other tumor types, however, the genotype-drug response associations are less defined and PIK3CA mutations, PTEN loss of function or both, or CDKN2A mutations have been reported as determinants of response." (PMID 22970424, 2012). "The PIK3CA mutation status in bone metastases samples appears to reflect the PIK3CA mutation status in the primary tumour." (PMID 22970388, 2012). "In order to assess the independent association of PIK3CA mutations and amplification with tumor size, tumor differentiation, tumor stage, lymph node metastasis and survival status, we conducted two multivariable logistic regressions." (PMID 22292935, 2012). "It is commonly deregulated in cancer through mutations or amplifications of the PIK3CA gene or through alterations in the function of upstream tumor suppressors such as PTEN." (PMID 23232172, 2012). "Specifically, KRAS, BRAF and PIK3CA mutations were detected in 10 (45%), 3 (14%) and 2 (9%) tumor specimens, respectively." (PMID 23144797, 2012). "We also observed high detection concordance for critical ‘hot-spot’ mutations (KRAS, BRAF, PIK3CA) in matched cpDNA and archival tumor tissue, and important differences between archival tumor and cpDNA." (PMID 23144797, 2012).
tumor (continued). "We analyzed characteristics and outcome of 90 consecutive patients with diverse advanced tumors and PIK3CA mutations and 180 wild-type PIK3CA controls matched by tumor type, gender, and age referred to the Clinical Center for Targeted Therapy." (PMID 23248156, 2012). "Data from genome-wide SNP arrays and flow cytometry were combined to determine the chromosomal dosage (allelic state) in these tumours, including mutation analysis of components of PIK3CA/AKT and MAPK pathways." (PMID 22675538, 2012). "PIK3CA mutation analyses in the primary tumor samples were performed blinded to the PIK3CA mutation status in the bone metastasis samples." (PMID 22970388, 2012). "The status of PIK3CA mutations was analyzed in 61 tumor tissues with 5 positive results, giving a total mutation rate of 8.2%." (PMID 22586484, 2012). "By using genetically defined isogenic cell models, we have been able to precisely define how PIK3CA mutations can influence metabolic pathways within a tumour." (PMID 23028762, 2012). "Our results demonstrate that a non-amplified, HER-2 IHC 2+ model responds completely to Trastuzumab targeted therapy, and importantly, that PIK3CA gene mutation negatively associates with Trastuzumab anti-tumor efficacy in a xenograft model of ESCC." (PMID 22935382, 2012). "Tumour-associated PIK3CA mutations are all somatic, mono-allelic single base changes that result in single amino acid substitutions." (PMID 23270540, 2012). "By contrast, PIK3CA Exon20 mutations were identified in 4 out of 57 tumor tissues (7.0%), all being H1047L." (PMID 22586484, 2012). "Mutations in PIK3CA, the gene encoding p110α, are oncogenic and are frequently reported in breast and colon cancers, where they are found in around 25% of human tumours." (PMID 23270540, 2012). "In this study of 90 patients with PIK3CA mutations and 180 wt PIK3CA controls (matched by tumor type, gender, and age) we identified having a history of DVT as the only clinical characteristic potentially associated with PIK3CA mutations." (PMID 23248156, 2012). "Primary tumor samples were obtained from four of the six cases analyzed for PIK3CA bone metastasis mutations." (PMID 22970388, 2012). "Activating mutations in PIK3CA gene have been described in several tumor types, and have been usually identified in two key regions in exons 9 (that encodes the helical domain of p110a) and 20 (that encodes the catalytic domain of p110a)." (PMID 24281308, 2012). "Fifty-seven patients had their tumor tissues available for detection of PI3K pathway activation (PIK3CA mutation and PTEN expression loss)." (PMID 21676217, 2011). "PTEN expression has been reported to be reduced in 49% of tumours, and 25% are reported to be characterised by mutation of PIK3CA." (PMID 21283818, 2011). "Somatic mutations in PIK3CA are also common in colon (18–32%), gastric (4–25%), endometrial (36%), liver (36%), brain (27%) and breast (18–40%) tumours." (PMID 22033276, 2011). "KRAS mutations were detected in 37 (33%), BRAF mutations in eight (7.2%) and PIK3CA mutations in 11 (9.8%, 8 in exon 9 and 3 in exon 20) primary tumours, respectively." (PMID 21283802, 2011). "K-Ras mutations were identified in 26.4% of tumours, and B-Raf and PIK3CA mutations in 8.8% of tumours, when automatic base calling software was used to assign mutation status." (PMID 21712828, 2011). "In total, an additional 14 tumours carrying K-Ras, B-Raf or PIK3CA mutations were identified by pyrosequencing analysis, including all mutations previously identified by dideoxy sequencing analysis." (PMID 21712828, 2011). "This discovery presaged identification of PIK3CA mutations in many human tumors, most prominently in tumors of the breast, colon, endometrium and thyroid gland." (PMID 21646685, 2011). "In tumor types with at least 5 PIK3CA mutations identified, analysis of frequency of mutations in the helical vs. kinase domain was carried out." (PMID 21829508, 2011).
tumor (continued). "Mutations in oncogenes including K-Ras, B-Raf and PIK3CA confer an important growth advantage to cancer cells and are found in more than one-third of all tumours." (PMID 21712828, 2011). "We demonstrate that across tumor types, patients often concomitantly harbor PIK3CA mutations and RAS/BRAF mutations." (PMID 21829508, 2011). "The V600E B-Raf mutation was found in 9 tumours (8.8% of tumours analysed), whereas the majority of PIK3CA mutations were found in codons 542 (3.9%) and 543 (2.9%), whereas only single tumours had mutations in codons 546 and 1047." (PMID 21712828, 2011). "Pyrosequencing analysis revealed mutation frequencies of 32.4, 11.5 and 13.7% for K-Ras, B-Raf and PIK3CA, respectively, thus significantly increasing the number of tumours with mutations in K-Ras, B-Raf or PIK3CA." (PMID 21712828, 2011). "The PTEN tumour suppressor gene and PIK3CA proto-oncogene encode proteins which contribute to regulation and propagation of signal transduction through the PI3K/AKT signalling pathway." (PMID 21473780, 2011). "Previous studies have reported that MSI, CIMP, BRAF mutation, PIK3CA mutation, and tumour LINE-1 hypomethylation are associated with prognosis and that lymphocytic infiltration is associated with many of these molecular variables." (PMID 22110523, 2011). "We analyzed frequencies of PIK3CA mutations in different disease types in which specific mutations were identified in at least 5 tumor samples." (PMID 21829508, 2011). "In confirmation of previous reports, K-Ras and B-Raf mutations were mutually exclusive in our tumour series, whereas mutations in K-Ras and PIK3CA, in and B-Raf and PIK3CA were found together, but occurred in only 7.8 and 2.9% of tumours, respectively." (PMID 21712828, 2011). "For squamous head and neck tumors a slight tendency to a greater prevalence of exon 9 mutations was observed among series, although the low incidence of PIK3CA mutations in this kind of neoplasm has probably prevented this tendency to stand out." (PMID 20398348, 2010). "These authors observed an unexpected significant down-expression of some Akt-regulated genes such as RPS6KB1 in their PIK3CA-mutated tumor series, but a normal level of AKT1 and mTOR transcripts." (PMID 21209903, 2010). "PI3K pathway alterations (PIK3CA gene mutations and/or amplification) have been observed in various human tumours." (PMID 20804548, 2010). "KRAS mutations were detected in 62 (37%), BRAF mutations in 13 (8%) and PIK3CA mutations in 26 (15%, 18 in exon 9 and 8 in exon 20) primary tumours, respectively." (PMID 19603024, 2009). "Patients with tumours harbouring an H1047R PIK3CA mutation or low expression of PTEN derived clinical benefit from lapatinib." (PMID 19844234, 2009). "We determined with confidence the mutational status for KRAS exon 2, BRAF exon 15, and PIK3CA exons 9 and 20 in 168 consecutive patients with mCRC, for whom a representative sample from the primary tumour was available for molecular analysis of DNA." (PMID 19603024, 2009). "Mutations in PIK3CA have since been identified in additional tumour types, such as hepatocellular carcinomas and ovarian cancers." (PMID 19285540, 2009). "We determined KRAS, BRAF and PIK3CA mutations in tumours from 168 patients treated for mCRC at two institutions." (PMID 19603024, 2009). "In most tumour lineages, including GBMs PIK3CA and PTEN mutations occur in a mutually exclusive manner." (PMID 19461960, 2009). "All KRAS, BRAF, and EGFR mutations were mutually exclusive across different tumor types while some PIK3CA mutant cases also harbored one of the other three mutations." (PMID 19826477, 2009). "PIK3CA mutations were identified in 26% of human breast tumor samples and cell lines at about equal frequency in tumor stages I to IV in another study." (PMID 19384426, 2007). "Detection of PIK3CA mutations in circulating tumor DNA may allow for real-time monitoring of disease and tailoring of targeted therapy." (PMID 41597409, 2026).
tumor (continued). "In addition, activating mutations in downstream effectors such as KRAS and PIK3CA, as well as loss-of-function mutations in the tumor suppressor PTEN, can drive constitutive signaling independent of RTKs, further limiting the efficacy of FGFR inhibition." (PMID 41584352, 2026). "Additionally, PIK3CA mutations enrich for MMP9+ macrophages that promote tumor angiogenesis through ANGPTL4 signaling." (PMID 41958669, 2026). "Understanding how mutant cells influence their microenvironment through paracrine signaling could offer new insights into tumor progression and metastasis in PIK3CA-mutated cancers." (PMID 40595500, 2025). "Further support for alpelisib’s biological activity was provided by a phase II study of alpelisib monotherapy, which demonstrated that early reductions in PIK3CA mutations detected in circulating tumor DNA (ctDNA) were strongly associated with improved outcomes." (PMID 40989687, 2025). "Therfore it is clearly possible that both PTEN hemi- and homozygous alterations in PTEN may influence treatment response in tumours with PIK3CA activating mutations." (PMID 40263319, 2025). "In addition, the PIK3CA variant c.1035T>A was present in every tumor and every sample with detectable translocation." (PMID 40489430, 2025). "In young women with Luminal A ductal carcinomas, lower rates of PIK3CA mutations (14% vs. 38%) were observed, which may in part explain the poor outcomes associated with these tumours." (PMID 39470669, 2025). "Moreover, 28% of PIK3CA mutations in circulating tumor DNA have been found in patients with advanced HER2 BC." (PMID 40050490, 2025). "Future studies will combine single-cell transcriptomics and functional validation experiments to explore how PIK3CA mutations directly or indirectly affect macrophage phenotypes and their roles within the tumor microenvironment at the molecular and cellular levels." (PMID 40328748, 2025). "The mutation frequency and tumour mutational burden (TMB) of the two groups were calculated using the maftools package in R. The mutation frequencies of PIK3CA, CDH1, GATA3, and MAP3K1 were higher in the “Low-risk” group compared to those of the “Low-risk” group." (PMID 41221278, 2025). "Tumor cells with PIK3CA mutations are resistant to drugs targeting epidermal growth factor receptor (EGFR) or erythroblastic leukemia viral oncogene homolog 2 (ERBB2), but may be more sensitive to mTOR and PI3K inhibitors." (PMID 41040523, 2025). "Whole exome sequencing revealedpathogenic variants ofKRAS and PIK3CA in the patient's tumor." (PMID 41311737, 2025). "•PIK3CA mutations are linked to tumor characteristics and NLR." (PMID 40472482, 2025). "Reports indicate that resistance mechanisms may include genetic mutations, tumor microenvironment factors, and activation of alternative signaling pathways, such as secondary mutations in PIK3CA, PTEN loss or inactivation, and ESR1 mutations." (PMID 40510030, 2025). "PIK3CA mutations, detectable through tumor tissue or ctDNA testing, are central to this approach." (PMID 39935426, 2025). "This patient’s tumor and cell line demonstrated the PIK3CA E542K hotspot mutation." (PMID 40500270, 2025). "Studies have shown that mutations of the PIK3CA gene mainly occur when the tumor is about to invade other tissues, which may lead to the enhanced lipid kinase activity, resulting in the out-of-control growth of cancer cells." (PMID 41040523, 2025). "Additionally, mutations in PIK3CA are known to increase the invasiveness of tumor cells, promoting their migration to the spleen." (PMID 41040533, 2025). "Pathogenic somatic KRAS and PIK3CA mutations were identified via WES of the original MLA tumor." (PMID 41311737, 2025).
tumor (continued). "The general objective of this study was to evaluate the frequency and clinical value of the ESR1 and PIK3CA mutations identified in cfDNA and to compare these results with primary tumor samples to evaluate if the mutation was originally present in the tumor or if it occurred during metastasis." (PMID 40076662, 2025). "Moreover, PIK3CA mutations reprogram the tumor microenvironment (TME): mutant tumor cells promote abnormal blood vessel formation and establish an immunosuppressive niche through the secretion of pro-inflammatory cytokines." (PMID 41281644, 2025). "No additional next-generation sequencing or broad genomic profiling was conducted on the tumor; this is a limitation of our report, as such analysis might have identified actionable mutations (for example, PIK3CA or ESR1 mutations) to further guide therapy." (PMID 40548112, 2025). "Whole-exome sequencing revealed pathogenic KRAS and PIK3CA mutations in the MLA tumor." (PMID 41311737, 2025). "PIK3CA mutations were found in 32% of early BC patients and were associated with favorable clinicopathologic characteristics, such as older age, ER positivity, lower grade, and smaller tumor size." (PMID 40080721, 2025). "In this review, we briefly introduce the function of the PI3K pathway and discuss how PIK3CA mutations rewire cell signaling, metabolism, and tumor microenvironment, as well as therapeutic strategies under development to treat patients with tumors harboring a PIK3CA mutation." (PMID 39717717, 2025). "Interestingly, RAS and PIK3CA mutations were detected in ctDNA in 10 and 15 cases, respectively, with low concordance to tumor tissue sequencing (31.3% for RAS and 47.1% for PIK3CA)." (PMID 40076838, 2025). "The patients were stratified into two subgroups based on their tumor-tissue PIK3CA mutation status." (PMID 40142329, 2025). "PIK3CA mutations remodel tumorigenic environments and promote tumor initiation and development." (PMID 39717717, 2025). "However, subsequent reprogramed tumor progression due to PI3K signaling pathway activation by PIK3CA mutations and/or PTEN-loss cause anti-HER2 resistance." (PMID 39920872, 2025). "One key reason is the spatial heterogeneity of PIK3CA mutations within tumor tissues." (PMID 40535135, 2025). "Several prognostic indicators demonstrated significant correlations with enhanced PFS and extended OS, including patients aged >50 years, PD-L1 expression levels (CPS ≥ 1 compared to <1 and CPS ≥ 10 versus <1), elevated tumor mutational burden, and presence of PIK3CA genetic alterations." (PMID 41409282, 2025). "This system ultimately achieves synergistic anti-tumor efficacy in PIK3CA-mutated tumors." (PMID 41281644, 2025). "Furthermore, mutations in the PIK3CA gene were associated with a lower risk of tumour recurrence (Hazard Ratio HR = 0.26; 95% CI: 0.11–0.62; p = 0.018)." (PMID 39768623, 2024). "However, the precursor [FA(18:2)−H]− was decreased, whilst [FA(20:3)−H]−, [FA(22:4)−H]− and [FA(22:5)−H]− were increased in PIK3CA-mutated tumor tissue, suggesting enhanced arachidonic acid metabolism." (PMID 39294437, 2024). "Additionally, a single case report demonstrated a partial tumor response in an advanced CCA patient with a PIK3CA mutation." (PMID 38730642, 2024). "Another unexplored area is mapping the tumor microenvironment in the context of PIK3CA gene mutations, which could provide greater accuracy in developing clinical strategies." (PMID 39369580, 2024).